IGF1R (insulin like growth factor 1 receptor)
Diseases named in the same sentence as IGF1R in open-access papers (continued):
Sharing a sentence is not in itself a finding about the gene and the disease.
infection (28 papers, 2012 to 2026). The state of being infected such as from the introduction of a foreign agent such as serum, vaccine, antigenic substance or organism. "Infection of M12 cells with an ERG-encoding retroviral vector led to a marked increase in IGF1R levels in comparison to control (uninfected) cells." (PMID 27285981, 2016). "Mechanistically, the molecule was found to suppress the viral F protein and IGF1R, thus limiting viral entry and infection." (PMID 40136667, 2025). "To investigate the relationship between RSV receptors and lipid rafts, we evaluated the impact of downregulating or stably overexpressing NCL or IGF1R on the infection of RSV A2 and B18537 strains in HEp-2 cells." (PMID 40742151, 2025). "While we initially saw very limited localization of NCL and IGF1R to lipid rafts, infection with RSV significantly increased the accumulation of both molecules on lipid rafts." (PMID 40742151, 2025). "The gene encoding IGF-1 was more highly expressed in the cluster 2 macrophages at 6 w after infection, and its receptor, IGF-1r, was more highly expressed in the neutrophils and macrophages." (PMID 39590301, 2024). "We observed altered levels of phosphorylated ERBB2 and IGF1R with differing kinetic patterns during infection." (PMID 38585651, 2024). "Strikingly, we observe DENV infection leads to phosphorylation of ERBB2 and IGF1R at different times during infection." (PMID 38585651, 2024). "The contribution of IGF-1 and IGF-1R to the mechanism of infection has been well documented in several virological studies, including studies on pneumonic viruses." (PMID 34452353, 2021). "On the contrary, IGF-1R immune staining reduced sharply due to ME-49 infection and attained marked expression in healthy controls." (PMID 32802484, 2020). "The infection with lenti-miR-223 inhibitor virus with 2 or 5 MOI blocked the IGF-1R reduction and reduced the AGE-induced apoptosis and the caspase 3 activity in MC3T3-E1 cells." (PMID 26893485, 2016). "IGF signaling was blocked by infection with adenoviruses expressing the dominant negative soluble form of IGF-1R (Ad-IGF-1R/482st)." (PMID 25945837, 2015). "Inhibition of FGFR-1 and IGF-1R decreased arg1 expression and restricted L. donovani replication in both in vitro and ex vivo models of infection." (PMID 24967908, 2014). "In the in vitro infection model, IGF-1R inhibition reduced parasite-induced expression of host arg1 mRNA and the intracellular parasite load, without decreasing cell viability." (PMID 24967908, 2014). "A dual luciferase assay was used to detect expression of IGF1R following the lentiviral infection of hESCs with miR-223 and the 3′UTR region of IGF-1R fused to a luciferase reporter." (PMID 24250812, 2013). "At 24 h post-infection (hpi), ZsGreen levels were similar between WT and hIGF1R-KO cells; however, by 72 hpi, viral spread was markedly reduced in hIGF1R-KO cells and correlated with IGF1R levels." (PMID 41880205, 2026). "To test whether reduced protein levels of EPHB4, ERBB2, FGFR2, or IGF1R impacted infection, we infected control and knockdown lines with DENV2 MON601 for 24 h." (PMID 38585651, 2024). "Nevertheless, one hypothesis that can be drawn from these data is that IGF1R activity is solely important early during infection, while ERBB2 has roles throughout the infection." (PMID 38585651, 2024). "Furthermore, RSV remained at the surface of the IGF1R–/– host cell even 90 min post-infection which suggests that internalization and actin rearrangement was severely impacted in mutant cells." (PMID 38015055, 2023). "We noted that there was a reduction in IGF1R expression 1 and 6 h after infection." (PMID 38015055, 2023). "Infection with AdCre-deleted IGF1R in IGF1R flox/flox VSMCs by >99%." (PMID 31562314, 2019).
infection (continued). "However, by immunoblot we found increased expression of the IGF-1R after 14 days post-infection, and somewhat unexpectedly the beta (cytoplasmic) domain of the IGF-1 receptor, which mediates intracellular signaling, was phosphorylated at these time points." (PMID 24967908, 2014). "Enhanced IGF1R might affect resistance to infection in mammals, consistent with the findings of experiments on nematodes that daf-2 mutants are resistant to bacterial pathogens." (PMID 22973545, 2012). "Therefore, we aimed to investigate whether IGF1R expression was downregulated during infection with RSV." (PMID 38015055, 2023). "Moreover, NF-κβ in ME-49 strain infection and IGF-1R in healthy controls were inspected in the perivascular spaces which question whether there is a potential cellular relationship or not." (PMID 32802484, 2020). "Further experiments confirmed that throughout the infection, RSV downregulates IGF1R expression on human airway epithelial cells." (PMID 40136667, 2025). "These receptors have been reported to interact with either the RSV fusion glycoprotein (RSV-F; ICAM-1, IGF1R, EGFR and NCL) or the RSV attachment glycoprotein (RSV-G; CX3CR1 and HSPGs) to coordinate infection." (PMID 38015055, 2023). "In parallel, positive regulators, such as HIF-1α, a master transcriptional regulator of glycolysis, and IGFBP5, capable of activating IGF1R-AKT to increase glycolysis, were significantly upregulated post infection." (PMID 37256871, 2023). "In those double-knockout (DKO) VSMCs, with both IR and IGF1R deleted, either chimeric receptor IR-ECD/IGF1R-ICD or IGF1R-ECD/IR-ICD was overexpressed using adenovirus vectors to mediate the infection." (PMID 31562314, 2019). "We confirmed these findings in BMDM exposed in vitro to L. donovani where parasite-induced IGF-1R phosphorylation was evident between 20 minutes and 24 hrs of exposure, and enhanced expression of IGF-1R protein was present at 24 hrs after infection." (PMID 24967908, 2014). "Conversely, neither actin-protrusions nor gaps in the cytoskeleton were observed during infection of IGF1R–/– cells with RSV." (PMID 38015055, 2023). "hDSCs infected with Lenti-IGF1R shRNA (LV-IGF1R-sh-hDSCs) revealed a significant reduction in IGF1R proteins 48 hours post-infection compared with non-inhibitory control shRNA (data not shown)." (PMID 27586516, 2016). "Chemical inhibition of signaling through the fibroblast growth factor receptor-1 (FGFR-1) or insulin-like growth factor-1 receptor (IGF-IR), or genetic knockdown of STAT6 led to reduced expression of arginase and enhanced control of the infection by macrophages." (PMID 24967908, 2014). "Since downregulation of IGF1R occurs promptly after infection, this may represent a mechanism used by RSV to restrict super-infection of a single cell and promote the infection of neighbouring, uninfected cells that have unimpeded expression of the viral receptor." (PMID 38015055, 2023). "Additionally, it has been shown that the RSV F protein can interact with insulin-like growth factor 1 receptor (IGF-1R), one of many cell surface receptors facilitating host cell infection by aiding in the translocation of proteins to the cell membrane necessary for RSV internalization." (PMID 36768699, 2023). "Similarly, the presence of a monoclonal antibody to the IGF1R reduced macrophage infection and arginase activity in PSG-treated cells but not in the saline-treated or isotype antibody controls." (PMID 29352310, 2018). "Furthermore, the expression levels of the receptor for IGF1 (Igf1r) increased by both the protein diet restriction alone and combined with infection, although the differences were not significant." (PMID 28397794, 2017). "However, inhibition of IGF1R does not completely restrict infection with RSV meaning that other viral receptors may play a role in mediating viral entry." (PMID 38015055, 2023).
infection (continued). "Although the infection does not appear to increase IGF-1 production, the IGF-1R is activated on splenic macrophages through a yet to be identified host or parasite factor." (PMID 24967908, 2014).
adenocarcinoma (23 papers, 2009 to 2025). A common cancer characterized by the presence of malignant glandular cells. "Genistein alters growth factor signaling through downregulation of tyrosine kinase-regulated proteins, EGFR, and IGF-1R in transgenic adenocarcinoma of the mouse prostate model." (PMID 36430361, 2022). "Genistein alters growth factor signaling by downregulating tyrosine kinase-regulated proteins, epidermal growth factor receptor (EGFR), and IGF-1R in transgenic adenocarcinoma in mouse prostate models." (PMID 36430361, 2022). "IGF1R mRNA expression was detectable in 1 (20%) normal and 5 (12%) adenocarcinoma of the colon samples." (PMID 21318160, 2010). "Adenocarcinoma and never-smokers have a higher expression of IGF-1R, which is associated with worse overall survival." (PMID 26793618, 2015). "Our study shows, for the first time, that the upregulation of GAS5 can overcome the resistance of human adenocarcinoma cells to EGFR-TKIs, at least partially by downregulating IGF-1R." (PMID 25925741, 2015). "The IGF-1R and its ligands, mainly IGF-1 and IGF-2, have been suggested to play pivotal roles in proliferation, survival and migration of adenocarcinoma cells of the colon/rectum." (PMID 22159423, 2012). "The other adenocarcinoma cell line H1975 showed only moderate activation of HER2, c-MET, and SHC pathways and a low activation of the IGF-1R pathway." (PMID 22091388, 2011). "The data revealed that miR-99a is significantly downregulated in NSCLC adenocarcinoma cells and it can be hypothesized that miR-99a may play a key role in NSCLC development and progression by modulating IGF-1R signaling." (PMID 25663868, 2015). "High expression of IGF-1R is associated with poor survival in surgically resected stage I adenocarcinoma which along with never-smokers had a higher expression of IGF-1R compared to squamous histology or smokers." (PMID 26793618, 2015). "However, a negative correlation between IGF-1 and IGF-1R expressions and caecal/colonic-adherent and fecal viable bacteria was observed (p < 0.05); thus, the significant protection against adenocarcinoma development observed in BF-treated groups is confirmed." (PMID 31480481, 2019). "However, it is still unknown or unclear the effect of different DM subclasses on squamous and adenocarcinoma cells at cellular mechanism of IGF-1 levels and overexpression of IGF-1R axis." (PMID 30705329, 2019).
metabolic disorders (15 papers, 2015 to 2025). "The findings indicate that AG-1024 (an IGF-1R inhibitor) attenuates the metabolic disorders in the rat model of DN." (PMID 37034500, 2023). "Taken together, these results suggest that this model for the acute inhibition of systemic IR/IGF1R signaling may be useful for investigating the recovery from metabolic disorders induced by impaired growth factor signaling." (PMID 28646158, 2017). "Thus, although still not studied in relation to successful aging, the observed interaction among genetic variants of IGF1R and PTPN1 in Danish long‐lived could reflect a conserved mechanism of cellular signalling, involved in the development of metabolic diseases and tumorigenesis." (PMID 29577582, 2018). "In OA, chondrocytes stress upregulate IGF1R in an attempt to repair, but sustained activation induces excessive PI3K mTOR signaling, which accelerates chondrocyte metabolic disorders, aging, and apoptosis, and promotes synovial vascular opacities to invade cartilage." (PMID 41261625, 2025). "Our data has shed new light on the emerging concept that repositioning calcium signalling-blocking drugs, such as CCBs, as an entirely novel class of IGF-1R-targeting chemopreventive agents without the potential deleterious toxicities of metabolic disorders." (PMID 27666821, 2016).
neurodegenerative disease (15 papers, 2010 to 2025). A disorder of the central nervous system characterized by gradual and progressive loss of neural tissue and neurologic function. "Recent work has also revealed a possible mechanistic link between IGF-1R and age-associated neurodegenerative diseases [reviewed in]." (PMID 20409077, 2010). "Since oxidative stress increases in the aging brain, and is associated with various neurodegenerative diseases, we assessed whether astrocytes could support neurons under conditions of oxidative stress, and whether loss of IGF1R abrogated the protection offered to neurons." (PMID 30056117, 2018). "Among neurodegenerative diseases, AD is the best-characterized pathology in terms of the role of IGF-1R, where it seems to play an important, albeit somewhat controversial, role." (PMID 39638246, 2024). "Rauskolb found the expression of IGF-1 and its corresponding receptor IGF-1R are dysregulated in patients with diabetes and neurodegenerative diseases." (PMID 30983995, 2019). "For instance, this additional mechanism would likely have impact onthe overall efficacy of IGF-1R down-modulation with respect to neurodegenerative diseases,where autophagy is beneficial." (PMID 23804751, 2013). "We also demonstrated that implantation of IGF1R+ hDSCs might be an applicable therapeutic strategy for neurodegenerative diseases." (PMID 27586516, 2016). "Human InsR, IGF1R, and IRR receptor tyrosine kinases (RTK) of the insulin receptor subfamily play an important role in signaling pathways for a wide range of physiological processes and are directly associated with many pathologies, including neurodegenerative diseases." (PMID 36835322, 2023). "Furthermore, increased insulin-like growth factor receptor (IGF-1R) protein levels and an activation of the phosphatidylinositol 3-kinase/Akt/glycogen synthase kinase 3 beta/β-catenin signaling pathway were identified in a mouse neurodegenerative disease model." (PMID 30406034, 2018). "We also report that IGF1R inhibition could be a beneficial treatment not only for NMJ control, but also for neurodegenerative diseases." (PMID 37717026, 2023). "We suggest that exploration of the mechanisms underlying IGF1R signalling that are independent of IGF-I action and reduce resilience to neurodegenerative disease with age might also identify novel therapeutic approaches." (PMID 38674097, 2024). "Considering that oxidative stress and glia-mediated inflammation also contribute to neurodegenerative diseases, the anti-inflammatory effects of IGF-1/IGF-1R still cannot be ruled out." (PMID 34445359, 2021).
prostate (10 papers, 2011 to 2022). "Our finding of hARtg to activate IGF1R axes in atypical basal cells explores a mechanism for AR's oncogenic role in prostate oncogenesis." (PMID 35902588, 2022). "The contribution of IGF-1R to prostate carcinogenesis and progression remains controversial, but epidemiological, preclinical and clinical results indicate that IGF-1R overexpression plays an important role in the pathogenesis of CRPC." (PMID 25906745, 2015). "We have demonstrated that the activation of the IGF-1R pathway through the increased expression of tissue-derived IGFs and the loss of IGFBP-3 is an early event in lung carcinogenesis." (PMID 26041671, 2015). "IGF-1 can signal through IGF-1R, IR, or IGF-1R+IR hybrid receptors; however, IGF-1 is unlikely to be involved in our model because KPTIRKO mice resisted HFD-induced kidney injury." (PMID 33400689, 2021).
cardiovascular diseases (7 papers, 2019 to 2025). "The NF-kB signaling pathway is also observed with molecules EGFR, INSR, RAF1 and IGF1R involved in the pathway, this pathway is involved in cardiovascular disease and angiogenesis." (PMID 37569355, 2023). "Consistently, the results of the present study indicated that miR-194-5p and IGF1R were involved in different pathways to regulate cardiovascular diseases." (PMID 36158838, 2022).
renal disease (7 papers, 2012 to 2025). "Surprisingly, genetic deletion of the insulin receptor (Insr) in podocytes but not of the IGF-1 receptor (Igf1r) attenuated renal disease of Phb2pko mice (Fig4A and B)." (PMID 25643582, 2015).
benign tumor (4 papers, 2011 to 2023). "Since IGF-2 dysregulation has been already shown in childhood and adult malignancies, as well as in benign tumors, it seemed reasonable to investigate the involvement of the IGF-2/IGF-1R pathway in primary pterygium, a benign tumor with premalignant features." (PMID 36901760, 2023).
CNS tumors (4 papers, 2015 to 2024).
hematological malignancies (4 papers, 2013 to 2020). "Ultimately, the direct targeting of mitochondria and the simultaneous deregulation of the IGF1R-Akt-mTOR signaling cascade make shikonin a promising compound for the treatment of hematological malignancies." (PMID 23861714, 2013). "Our results indicate that inhibiting the IGF1R-Akt-mTOR signaling cascade is a new cellular mechanism of shikonin strengthening its potential for the treatment of hematological malignancies." (PMID 23861714, 2013). "In these malignancies, Klotho was elucidated to be a modulator of several signaling pathways, including the FGF signaling, insulin-like growth factor-1 receptor (IGF-1R), and Wnt pathways, which are also involved in the pathogenesis of hematological malignancies." (PMID 28153033, 2017). "Induction of IGF-1R signaling was involved in the pathogenesis of hematological malignancies." (PMID 28153033, 2017). "The IGF-1R pathway plays a vital role in the development of hematological malignancies." (PMID 28153033, 2017).
inflammation (4 papers, 2016 to 2024). Aberrant reaction of the microcirculation characterized by movement of fluid and leukocytes from the blood into extravascular tissues. "This is the first report of the functional implication of IGF1R in acute lung inflammation using a BLM mouse model." (PMID 28655914, 2017). "We here showed that loss of IGF-1R in these cells leads to: (I) altered cellular morphology; (II) regulation of cellular transcriptome affecting adhesive, metabolic and immune functions; (III) worsened autoimmune CNS inflammation." (PMID 36890580, 2023).
retinopathy (4 papers, 2010 to 2024). "In addition, local upregulation of IGF1 has been shown to trigger blood‒retinal barrier breakdown, and accordingly, humans with retinopathy with marked gliosis exhibited upregulation of IGF1R expression." (PMID 38252153, 2024).
neurodevelopmental disorder (3 papers, 2019 to 2024). A behavioral and cognitive disorder with onset during the developmental period that involves impaired or aberrant development of intellectual, motor, or social functions. "These terminal events impact IGF1R, CNTNAP2, and DPP6, shown to be strongly associated with neurodevelopmental disorders." (PMID 31475484, 2019).
neurological disorders (3 papers, 2017 to 2025). "Recent studies suggest that IGF-1 and its receptor IGF-1R are involved in the pathogenesis of neurological diseases." (PMID 41256775, 2025). "We speculate that the IGF1R gene may play a role in the etiology of neurological disorders and of gonadal abnormalities in these patients." (PMID 28899882, 2017).
skeletal dysplasia (3 papers, 2014 to 2025). Any Mendelian diseases that affects growth and development of the skeleton. "Additionally, various molecular defects in the Igf1 and Igf1r genes in humans have been associated with severe intrauterine growth retardation and impaired skeletal maturation, but not with truncated limbs or severe skeletal dysplasia." (PMID 24859417, 2014).